GFRA1 (GDNF family receptor alpha 1)
Diseases named in the same sentence as GFRA1 in open-access papers (continued):
Sharing a sentence is not in itself a finding about the gene and the disease.
cystitis (1 paper, 2015). Inflammation of the urinary bladder. "Furthermore, we have previously reported that widespread upregulation of GFRα1-IR can be detected in sacral dorsal horn following experimental cystitis, which should only affect a more restricted range of visceral afferents than those damaged by pelvic and hypogastric nerve transection." (PMID 25914629, 2015).
epilepsy (1 paper, 2018). A brain disorder characterized by episodes of abnormally increased neuronal discharge resulting in transient episodes of sensory or motor neurological dysfunction, or psychic dysfunction. "In addition, the upregulation of GDNF and GFRA1 has been reported in stroke (ischemia) and epilepsy (seizure disorder)." (PMID 29617307, 2018).
Hyperglycemia (1 paper, 2025). An increased concentration of glucose in the blood. "Here, the induction of Gfra1 and Nrg1 may reflect adaptive metabolic or growth-factor signaling in response to hyperglycemia, whereas decreased expression of Aspdh and Mtch2 suggests compromised mitochondrial function and heightened oxidative challenges." (PMID 40920692, 2025).
in situ carcinoma (1 paper, 2013). A malignant epithelial neoplasm which is confined to the epithelial layer without evidence of further tissue invasion. "We have recently shown that the GDNF co-receptor GFRA1 is over-expressed in human in situ carcinoma (CIS) and in intratubular and invasive seminoma." (PMID 23613711, 2013).
Infertility (1 paper, 2016). "Each Gdnf-, Gfra1- and Ret-deficient mouse showed severe SSC depletion and infertility." (PMID 27769051, 2016).
malignant melanomas (1 paper, 2010). "On the other hand, the present results showed that not only RFP-RET but also c-Ret, Gfra1 and Gdnf expression levels in malignant melanomas were definitely increased compared with those in benign melanocytic tumors in RET-mice." (PMID 20422010, 2010). "The difference in Gfra1 and Gdnf transcript expression levels between benign tumors and malignant melanomas from RET-mice was statistically significant (p<0.05)." (PMID 20422010, 2010). "Gfra1 and Gdnf transcript expression levels in malignant melanomas were also 13-fold and 5-fold upregulated, respectively, compared with those in benign melanocytic tumors." (PMID 20422010, 2010). "Moreover, we for the first time demonstrated not only GFRa1 protein expression but also GDNF-mediated c-RET kinase activation via phosphorylated tyrosine 905 in human malignant melanoma cells." (PMID 20422010, 2010). "In this study, we showed that expression levels of intrinsic c-Ret, glial cell line-derived neurotrophic factor (Gdnf) and Gdnf receptor alpha 1 (Gfra1) transcripts in malignant melanomas from RET-transgenic mice were significantly upregulated compared with those in benign melanocytic tumors." (PMID 20422010, 2010). "Then we showed that transcript and protein of GFRa1, which is essential for c-RET/GDNF signaling, was expressed in malignant melanoma cells by real-time PCR and immunohistochemistry." (PMID 20422010, 2010). "We next examined the expression levels of c-RET, GFRa1 and GDNF in primary-cultured normal human epithelial melanocytes and human malignant melanoma cell lines (G361, SK-Mel28, MNT-1 and HM3KO)." (PMID 20422010, 2010). "Our results showed that transcript expression levels of c-RET and GDNF in MNT-1 and HM3KO human malignant melanoma were definitely higher than those in NHEM cells, while GFRa1 expression levels were comparable in these cells." (PMID 20422010, 2010). "These dynamics of intrinsic c-Ret/Gfra1/Gdnf and introduced RFP-RET signaling in melanocytic tumors from RET-mice encourage us to examine the correlation between RET and human malignant melanoma." (PMID 20422010, 2010). "The expression levels of c-RET, GFRa1 and GDNF in G361 and SK-Mel28 human malignant melanoma cells were definitely lower or undetectably low compared with those in NHEM cells." (PMID 20422010, 2010). "We then showed that c-RET and GDNF transcript expression levels in human malignant melanoma cell lines (HM3KO and MNT-1) were higher than those in primary cultured normal human epithelial melanocytes (NHEM), while GFRa1 transcript expression levels were comparable among NHEM, HM3KO and MNT-1." (PMID 20422010, 2010). "In fact, not only GDNF-mediated c-RET kinase activation but also GFRa1 expression in human malignant melanoma cells has still not been elucidated." (PMID 20422010, 2010).
meningioma (1 paper, 2017). A generally slow growing tumor attached to the dura mater. "Importantly, decreased H3K27ac binding was associated with decreased GFRA1 expression in atypical NF2 versus benign NF2 meningiomas (FDR 6.2 × 10−5 fold change log FC=9.54)." (PMID 28195122, 2017).
migraine (1 paper, 2019). "The associations of six SNPs identified from our previous study, including TRPM8 rs10166942, LRP1 rs1172113, DLG2 rs655484, GFRA1 rs3781545, UPP2 rs7565931, and GPR39 rs10803531, and migraine endophenotypes, including chronic migraine and allodynia were tested." (PMID 31842742, 2019).
mullerian aplasia (1 paper, 2019). "Efforts to identify causative genes within regions of copy number variation in patients affected with Mullerian aplasia have turned up candidate genes such as KHDRBS2, and GFRA1, which we see uniquely expressed in the ‘inhibited progenitor’ cluster." (PMID 31232694, 2019).
neuropathy (1 paper, 2018). A disorder affecting the nervous system that manifests with pain, tingling, numbness, and/or muscle weakness. "Despite this, we showed that the expression especially of NGF, NGFR, NTRK1, GFRA1, GFAP, and GDNF was upregulated in patients with severe neuropathy as compared to healthy subjects and diabetic patients with subclinical neuropathy." (PMID 30648113, 2018).
oligodendroglioma (1 paper, 2013). A well-differentiated (WHO grade II), diffusely infiltrating neuroglial tumor, typically located in the cerebral hemispheres. "Overexpression of GFRA1 has been reported in chemotherapy-sensitive oligodendrogliomas." (PMID 23544068, 2013).
pancreatic ductal adenocarcinoma (1 paper, 2020). An infiltrating adenocarcinoma that arises from the epithelial cells of the pancreas. "Intriguingly, human pancreatic ductal adenocarcinomas demonstrated great variability in their expression of GFRα1, indicating alternative sources of GFRα1 in perineural invasion by these cancer cells." (PMID 32737575, 2020).
peripheral nerve injury (1 paper, 2025). Injury to a peripheral nerve. "Here, it is shown that GFRα1 released from repair Schwann cells (RSCs) functions as a ligand in a GDNF‐RET‐independent manner to promote axon regeneration after peripheral nerve injury (PNI)." (PMID 39630029, 2025). "Schwann cells increased the expression of GFRα1, which is known as a receptor for Glial cell line derived neurotrophi factor (GDNF), after peripheral nerve injury." (PMID 39630029, 2025).
pituitary adenomas (1 paper, 2021).
polyp (1 paper, 2014). A usually exophytic mass attached to the underlying tissue by a broad base or a thin stalk. "53.9 and 51.3% of LSCC samples were positive for ARTN and GFRα1, respectively, whilst only 26.9% of normal squamous epithelium from patients with polyp were positive for ARTN and GFRα1 (P=0.015 and P=0.031, respectively)." (PMID 25120606, 2014). "The results revealed that the expression of ARTN and GFRα1 was significantly increased in LSCC compared with polyp tissue samples." (PMID 25120606, 2014).
psychosis (1 paper, 2023). "Here, we analysed the effect of acute, chronic, and embryonic methamphetamine, a drug known to enhance the risk of psychosis, on Gdnf and its receptors, Gfra1 and Ret, as well as on monoamine metabolism-related gene expression in the mouse brain." (PMID 37759827, 2023). "Our results may guide future experiments and precision medicine development for methamphetamine-induced psychosis using GDNF/GFRa1/RET antagonists." (PMID 37759827, 2023). "Our results suggest a potential mechanism as to how methamphetamine elicits individual psychosis risk in young adults—variation in initial striatal GDNF induction and subsequent GFRα1 and RET downregulation may determine individual susceptibility to psychosis." (PMID 37759827, 2023). "This is important, as the observed dual effect suggests a mechanism as to how methamphetamine induces psychosis with incomplete penetrance—individuals with higher GDNF induction and less prominent GFRa1/RET downregulation are more likely to develop psychosis." (PMID 37759827, 2023).
renal carcinoma (1 paper, 2017). A carcinoma arising from the epithelium of the renal parenchyma or the renal pelvis. "Out of the unique set of genes detected by BNNPT, a few were reported to be relevant to renal cancer or disease: CDCP1, GSTT1, E2F3, MAPK1, SALL4, SIRT1, ADAMTS13, Gfrα1, ASPH, MIR17HG, APOE, BMP4, RCOR1, NUMB and SEC63." (PMID 28986523, 2017).
renal cystic dysplasia (1 paper, 2022). "The GFRA1 missense variant c.362A>G was associated with BRA, while the missense variant in NPNT: c.56C>G was associated with severe renal cystic dysplasia." (PMID 36292572, 2022).
cancer (41 papers, 2010 to 2025). A tumor composed of atypical neoplastic, often pleomorphic cells that invade other tissues. "The GDNF family exhibits diverse roles in cancer, including an association with therapy resistance in ER+ BC, highlighting GFRA1 as a potential target." (PMID 39372749, 2025). "HCC1500 and MCF7, both ER+, expressed detectable levels of GFRα1 protein, while MDA-MB-231 and MDA-MB453, both ER-, did not, consistent with the reported association of ER and GFRα1 expression in human cancer patients." (PMID 33233403, 2020). "The increased expression of APE1 induced by various cancer risk factors including ROS activates NF-κB1, followed by inducing GFRα1 expression via binding on GFRα1 promoter." (PMID 32438692, 2020). "Recent studies provide evidence that GFRA1 is implicated in tumorigenesis and cancer progression." (PMID 29617307, 2018). "GFRA1 has also been implicated in cancer cell progression and metastasis." (PMID 29617307, 2018). "However, recent studies have reported that GFRA1 also is implicated in cancer signaling." (PMID 29617307, 2018). "Among them, several up-regulated genes are known to be involved in the formation of tumor microenvironments (Carbonic anhydrase 2 (CA2)), cancer chemoresistance (Cannabinoid receptor 1 (CNR1), GFRA1) and cancer recurrence after therapy (RGL3)." (PMID 36769365, 2023). "GFRA1 plays a crucial role in the formation and maintenance of the nervous system, whose abnormal expression level is frequently observed in numerous cancer cells." (PMID 36106103, 2022). "CircRNA GFRA1 (circGFRA1) was dysregulated in many cancer samples and acted as an independent marker for prediction of survivals in various cancer patients." (PMID 33431945, 2021). "We found that GFRA1 is associated with AKT phosphorylation and c-Jun expression, which induce EMT in several cancers." (PMID 33175846, 2020). "Either of downregulated APE1 or GFRα1 expression using small interference RNA (siRNA) inhibited GDNF-induced cancer cell proliferation." (PMID 32438692, 2020). "The authors found that RET activation, MAPK pathway activity, and cancer cell migration towards GDNF were increased upon exposure to soluble GFRα1." (PMID 32737575, 2020). "GFRA1 released by nerves enhances cancer cell perineural invasion, whose expression is reduced in tumor samples of TCGA-LUAD and TCGA-LUSC compared with normal samples." (PMID 30400837, 2018). "We used the Oncomine Power Tools gene expression database to interrogate the expression of GFRA1 across multiple major cancer types and distal normal tissues." (PMID 29796165, 2018). "In cancers with heterogenous GFRA1 expression, the antitumor activity of GFRA1-PBD hinges on the capacity of the ADC to elicit bystander activity in target-negative cells." (PMID 29796165, 2018). "GFRA1 cell surface receptor density was interrogated in various cancer cell lines reported to have high GFRA1 RNA expression levels." (PMID 29796165, 2018). "Further understanding of GFRA1 expression will provide a major clue to solve the riddle of cell outcome, neuronal cell death and cancer cell proliferation and survival." (PMID 29617307, 2018). "Consistent with this notion, a recent study found that peripheral nerves secrete both GDNF and GFRa1, which attracts perineural invasion of heterogeneous cancer cells, some of which expresses Ret and Gfras, while some express only Ret." (PMID 25838128, 2015). "Moderate or strong expression of GFRα1 and GFRα3 mRNA was predominantly localized in the carcinoma cells with an infrequently positive signal located in stromal cells." (PMID 23351331, 2013). "We next examined expression levels of intrinsic c-Ret, Gfra1 and Gdnf transcripts in benign and malignant tumors from RET-mice." (PMID 20422010, 2010). "Another pathway related to cancer growth is the GDNF family receptor alpha 1 protein (GFRA1)." (PMID 40061926, 2025). "Recent findings show that GFRA1 also plays a role in cancer cell progression and metastasis." (PMID 37501725, 2023).
cancer (continued). "Cancer cell migration induced by macrophage-derived GDNF depends on GFRα1 co-receptor and RET, as demonstrated by the inhibitory effect observed in knock down experiments with cells lacking GFRα1 co-receptor and the use of RET inhibitor (pyrazolopyrimidine-1, PYP1)." (PMID 32555170, 2020). "Collectively, the results from these investigations provide support to the idea that GFRA1 may be applicable as a biomarker and/or therapeutic target for cancer." (PMID 29617307, 2018). "Conversely, one could envision that peripheral nerve expression of GFRA1 has the potential to lead to issues of toxicity, particularly among heavily pretreated cancer patients who often suffer from preexisting peripheral neuropathy." (PMID 29796165, 2018). "Furthermore, decreased release of soluble GFRα1 from DRG inhibits migration of cancer cells towards nerves in vivo providing further evidence that GFRα1 expression is important in facilitating PNI." (PMID 29334991, 2018). "GFRA1 protein released by the microenvironment can promoted may enhance cancer cell PNI through activation of RET." (PMID 27566576, 2016). "Similarly, aberrant expression of GFRA1 has been often observed in cancer." (PMID 29617307, 2018). "However, recent evidence suggests that GFRA1 is robustly involved in cancer progression." (PMID 29617307, 2018). "GFRA1, probably upregulation of AKT and Extra-cellular Signal Regulated Kinase (ERK) pathways in cancer cells." (PMID 40061926, 2025). "Among patients with lacrimal ACC, GFRα1 and RET expression were positively correlated with PNI presence and cancer recurrence." (PMID 39906323, 2024). "The GFRα1 released by nerves further enhances RET activation and amplifies cancer cell perineural invasion." (PMID 38099290, 2023). "In the tumor microenvironment, GFRα1 was demonstrated to be released by nerves, enhancing perineural invasion (PNI) and serving as a guidance signal for cancer cell migration." (PMID 35582425, 2022). "Even though GFRα1 expression varies widely in different cancer cells, both GFRα1 and its ligand GDNF can be released from the tumor microenvironment and cooperate to facilitate cancer invasion." (PMID 35582425, 2022). "Further, several genes at central nodes in the sub-network have cell-cell and cell-matrix adhesion functions and were described in numerous human cancer entities: CTNNA1, NCAM1, and GFRA1." (PMID 27172797, 2016). "Except for TBX5, all 5 genes (GFRA1, SLC6A5, SOX1, SOX14 and TBX20) were significantly differentially methylated between normal and cancer tissues with a high methylation frequency in both ADC and SCC." (PMID 27738327, 2016). "Similar to mRNA expression, GFRα1, GFRα3 and SDC3 proteins were localized in the cytoplasm of epithelial cells of mammary ducts and acini in BBD or carcinoma cells in MC." (PMID 23351331, 2013). "Previous studies showed that overexpression of c-RET, GFRa1 and/or GDNF indicated poor prognosis in human pancreatic and bile duct carcinomas." (PMID 20422010, 2010). "During PNI, a soluble form of GFRα1 released by normal nerves facilitates neural tracking regardless of GFRα1 expression in cancer cells." (PMID 35582425, 2022). "Here, we demonstrate that GFRα1 is expressed in two luminal cancer cell lines (MCF7, HCC1500) and not in one HER2+ (MDA-MB-453) and one triple negative (MDA-MB-231) cell line." (PMID 33233403, 2020). "Once GFLs bind to GFRA1, it transfers its signals to co-receptor RET which can activate downstream targets like Src kinase, RAS/MAPK, PLCγ, or PI3K/AKT, resulting in cell proliferation, migration and survival in cancer and neuronal cells." (PMID 29617307, 2018). "Besides, soluble GFRα1 released from the DRG cells after binding with the cancer-derived GDNF activates the MAPK pathway, resulting in cells’ enhanced migratory potential and, in effect, nerve invasion by the cancer cells." (PMID 39906323, 2024). "Interestingly, dorsal root ganglia can release soluble GFRα1 even in the absence of cancer cell expression of GFRα1." (PMID 38099290, 2023).
cancer (continued). "Once GDNF/GFRA1/RET makes a complex, it activates various signaling pathways, such as RAS/MAPK, PI3K/Akt and PLCγ pathway, which contribute to cell proliferation, adhesion, migration, differentiation and survival and which contribute to the pathogenesis of both cancer and neuronal disease." (PMID 29617307, 2018). "Unlike neuronal cells, GFRA1 overexpression induces tumor progression in cancer cells." (PMID 29617307, 2018).